PDE5A (phosphodiesterase 5A)
Diseases named in the same sentence as PDE5A in open-access papers (continued):
Sharing a sentence is not in itself a finding about the gene and the disease.
infarction (1 paper, 2016). A localised pathological necrosis of tissue resulting from obstruction of the blood supply usually by a thrombus, an embolus, or vascular torsion. "Furthermore, a central role of the PKG-I activity in the cardiogenic process is also demonstrated by tadalafil treatment, a cGMP-specific phosphodiesterase 5A (PDE5A) inhibitor, which proved to promote survival and proliferation of mesenchymal stem cells in a rat model of infarction." (PMID 27840646, 2016).
mitral valve regurgitation (1 paper, 2015). "Phosphodiesterase 5A (PDE5A) inhibition has demonstrated positive cardiac effects in various disease models, including mitral valve regurgitation." (PMID 26543727, 2015).
Osteopenia (1 paper, 2021). Osteopenia is a term to define bone density that is not normal but also not as low as osteoporosis. "Recently it is reported that PDE5 inhibitors could enhance osteoblastic bone formation by targeting PDE5A and reverse osteopenia in ovariectomy mice by an osteogenic mechanism." (PMID 33776932, 2021).
paroxysmal atrial fibrillation (1 paper, 2016). Episodes of atrial fibrillation that typically last for several hours up to one day and terminate spontaneously. "The proteomics results found increased binding to PDE5A in paroxysmal atrial fibrillation patients to impair proteins involved in electrical and calcium remodeling, a result that has implications in the understanding and treatment of atrial fibrillation." (PMID 27980500, 2016).
skin cancer (1 paper, 2025). "We examine the diverse All of Us dataset and identify genetic ancestries, lifestyle, social determinants of health and PDE5a inhibitor use as independent risk factors for skin cancer." (PMID 41162377, 2025). "Overall, these results show that in the multiethnic logistic regression model multiple factors, including cancer history, sex, SDOH, lifestyle, ﻿PDE5a inhibitor use and genetic ancestries, independently affect a person’s risk to develop any skin cancer." (PMID 41162377, 2025). "However, a causal link between ﻿PDE5a inhibitors and skin cancer is difficult to establish because of the interconnectedness of lifestyle and socioeconomic factors that we show in our study." (PMID 41162377, 2025). "Here, the authors identify genetic ancestry, lifestyle, social determinants of health, and PDE5a inhibitor use as independent risk factors for skin cancer in the All of Us dataset, and integrate these factors into an XGBoost multiethnic model for identifying patients with skin cancer." (PMID 41162377, 2025). "In this study, we leveraged the expansive All of Us (AoU) dataset to delve into the intricate relationships between skin cancer, genetic predispositions, lifestyle factors, SDOH, and the utilization of ﻿PDE5a inhibitors." (PMID 41162377, 2025). "In general, three main factors influence skin cancer risk: genetics, environment (intended as both lifestyle and SDOH), and the use of ﻿PDE5a inhibitors." (PMID 41162377, 2025). "In this study, while our focus did not encompass establishing causality between ﻿PDE5a inhibitors and skin cancer, we show that ﻿PDE5a inhibitor use is independently associated with skin cancer risk in individuals of European ancestries, and contributes to the high accuracy of our predictive model." (PMID 41162377, 2025). "It has been hypothesized that differences in skin cancer risk and severity are influenced by non-genetic factors including age, sex, SDOH, drinking, smoking, and PDE5a inhibitor usage." (PMID 41162377, 2025).
urothelial carcinoma (1 paper, 2021). A malignant neoplasm derived from the transitional epithelium of the urinary tract (urinary bladder, ureter, urethra, or renal pelvis). "The results demonstrated low expression of PDE5A, RECK, ZEB2, and CYBRD1 in urothelial carcinoma tissue." (PMID 33987019, 2021). "PDE5A, RECK, ZEB2, and CYBRD1 play essential roles by interacting with other miRNAs and genes in urothelial carcinoma networks which are represented by purple circles." (PMID 33987019, 2021).
tumor (84 papers, 2010 to 2025). "In this study, we constructed a Meo-PEG-S–S-PLGA-based reduction-responsive nanoplatforms capable of delivering circPDE5A and PDE5A-500aa overexpression plasmids to tumor cells, which can successfully inhibit ESCC growth and metastasis in vivo." (PMID 38658954, 2024). "CircPDE5A encodes a novel protein (PDE5A‐500aa) that directly binds to PIK3IP1, thereby reducing PI3K/AKT signaling activity and inhibiting tumor proliferation and metastasis in ESCC." (PMID 39584047, 2024). "PDE5A also potentially presents tumor suppressor genes, as identified by comparing the expression between normal and tumor specimens." (PMID 33987019, 2021). "PDE5A is also a potential tumor suppressor gene, as identified by comparing the expression levels between normal and tumor specimens from 20 patients." (PMID 33987019, 2021). "In addition, researchers used the Meo–PEG–S–S–PLGA platform to load circPDE5A and protein PDE5A‐500aa for tumor therapy, and the results showed that it can effectively alleviate tumor progression." (PMID 39584047, 2024). "Furthermore, by using paired UTUC and normal tissues from 20 patients, lower PDE5A expression was also demonstrated in tumor specimens." (PMID 33987019, 2021). "Another theory proposed that PDE5A is related to hypoxia in tumor microenvironments." (PMID 33987019, 2021). "The findings demonstrated lower expression of PDE5A in tumour specimens than in normal tissues." (PMID 33987019, 2021). "To further clarify whether PDE5A is associated with UC, we evaluated PDE5A expression through real-time PCR from the paired UTUC tissues (normal–tumor) of 20 patients, in total, 40 samples." (PMID 33987019, 2021). "Therefore, we hypothesized that PDE5A plays the role of a tumor suppressor in UC." (PMID 33987019, 2021). "Six sEV proteins were identified, namely, GCLM, KEL, APOF, CFB, PDE5A, and ATIC, which properly distinguished normal control, early neoplasia, and advanced neoplasia patients from each other." (PMID 34589434, 2021). "The present study identified six sEV proteins, namely, GCLM, KEL, APOF, CFB, PDE5A, and ATIC, that could distinguish early neoplasia, advanced neoplasia, and normal controls from each other well." (PMID 34589434, 2021).
cancer (75 papers, 2011 to 2025). A tumor composed of atypical neoplastic, often pleomorphic cells that invade other tissues. "This association was discovered after the biological significance of downregulating PDE5a expression by cancer driver mutations in genes within the RAS/BRAF/MEK/ERK pathway was realized." (PMID 41162377, 2025). "Our data elucidated that the function of MEX3A in suppressing CRC cell autophagy relies on the PDE5A pathway, providing the first evidence of PDE5A as a critical regulator in cancer cell autophagy." (PMID 38565536, 2024). "As a result, seven genes (FGF10, SERINE2, LSAMP, STXBP5, PDE5A, GLI2, FRMD6) were screened to develop the cancer associated fibroblasts (CAFs)-related risk signature (CAFRS)." (PMID 37280069, 2023). "Removing eight of the risk variables (sex, cancer history, SDOH, lifestyle, genotype PCs, geo = longitude and latitude, ﻿PDE5a inhibitors, and predicted ancestry) one at a time from the XGBoost multiethnic model had minimal effects on its accuracy (mean F1 statistic = 0.807 across eight variables)." (PMID 41162377, 2025). "Moreover, the PDE5A gene showed the highest correlation with survival risk, whereas the RHOB gene had the lowest correlation in diverse cancer types." (PMID 34824999, 2021). "Our study confirmed that expression levels of PDE5A are increased in CRN patients, which previous studies describe in various cancer cell lines." (PMID 27927168, 2016).
cardiovascular diseases (26 papers, 2013 to 2025). "PDE5A belongs to the PDE family, and targeted regulation of PDE5A is considered an effective target for the treatment of cardiovascular disease." (PMID 38332893, 2024). "The early findings thus pointed to PDE9A as a novel therapeutic target in cardiovascular disease, distinct from the well-known PDE5A, by suggesting that blocking PDE9A could augment NP/cGMP signaling and mitigate cardiac stress responses." (PMID 40650137, 2025).
cardiac disease (8 papers, 2010 to 2025). "Increased expression/activity of Pde5a was detected in cardiovascular alterations of human patients and in animal models of cardiac diseases." (PMID 40659490, 2025). "The different cAMP/cGMP ratio observed after Sildenafil treatment in Pde5a+/+ mice under the two TAC conditions, seems to correlate with increased phosphorylation of ERK1/2 kinases and up-regulation of Bcl2 as previously reported in another cardiac disease model." (PMID 40659490, 2025).
colon polyps (1 paper, 2025). "The drug Exisulind, targeting PDE5A, has potential applications in treating LC, colorectal adenomatous polyposis, and colon polyps." (PMID 40853920, 2025).
PDE5A also shares sentences with these, for which no sentence is quoted: benign prostatic hyperplasia (24 papers); endothelial dysfunction (21); Priapism (20); myocardial infarction (14); depression (13); type 2 diabetes (13); sexual dysfunction (10); angina (9); chronic obstructive pulmonary disease (9); metabolic syndrome (9); diabetic cardiomyopathy (8); glioblastoma (8); Hyperglycemia (8); hypogonadism (8); Insulin resistance (8); kidney disease (8); portal hypertension (8); chronic kidney disease (7); Cirrhosis (7); neurodegenerative disease (7); thyroid cancer (7); head and neck squamous cell carcinoma (6); neurological disorders (6); prostatitis (6); Right ventricular hypertrophy (6); dyspepsia (5); gastric cancer (5); hearing loss (5); liver cirrhosis (5); myeloma (5).
A further 222 diseases each share a sentence with PDE5A in 5 papers or fewer.